CSF2 (colony stimulating factor 2)
Diseases named in the same sentence as CSF2 in open-access papers (continued):
Sharing a sentence is not in itself a finding about the gene and the disease.
diabetes (55 papers, 2010 to 2025). "The serum anti-CSF2 antibody (s-CSF2-Ab) levels were significantly higher in patients with acute ischemic stroke (AIS), acute myocardial infarction (AMI), diabetes mellitus (DM), and chronic kidney disease (CKD) compared with healthy donors (HDs)." (PMID 36844744, 2023). "The expression of CSF2 was not related to age, gender, smoking status, BMI, diabetes status, or tumor size but significantly correlated with T stage and histologic grade." (PMID 38817867, 2024).
glioblastoma (49 papers, 1994 to 2025). The most malignant astrocytic tumor (WHO grade IV). "Glioblastoma EVs in the tumor microenvironment then stimulate local astrocytes to produce cytokines including CSF2 and 3, IL-4, -6, -10, and -13, which together promote a T-helper type 2 immunosuppressive phenotype." (PMID 38188300, 2023). "For instance, CSF2 has been shown to attract and sustain the survival of microglia and macrophages in the glioblastoma microenvironment, promoting their pro-tumor polarization." (PMID 37865637, 2023). "Further, we determined the levels of CSF2 mRNA using quantitative PCR and its protein by ELISA in five glioblastoma cell lines, normal brain samples and normal human astrocytes (NHA)." (PMID 32390004, 2020). "On the other hand, the protein coding Csf2 (granulocyte-macrophage colony-stimulating factor), is typically upregulated in glioblastoma patients and believed to promote alternative activation of microglia." (PMID 28659758, 2017). "EVs from patients suffering from glioblastoma (GBM) are capable to polarize CD14+ and CD163+ monocytes toward the M2 anti-inflammatory phenotype, enhancing blood serum concentrations of colony-stimulating factor 2 and 3, as well as to detect interleukin-2, -4, and -13." (PMID 37511010, 2023).
pneumonia (48 papers, 2010 to 2025). An acute, acute and chronic, or chronic inflammation focally or diffusely affecting the lung parenchyma, caused by an infection in one or both of the lungs (by bacteria, viruses, fungi, or mycoplasma.). "The knocking in of Csf2 and Il3 was shown to increase the susceptibility of S. aureus in the context of acute pneumonia." (PMID 28523002, 2017). "Seven hub genes, IL4, IL6, CSF2, IFNG, IL1B, TNF and IL17A, were responsible for Experimental Lung Inflammation, Pneumonitis, Pneumonia and Lobar Pneumonia." (PMID 36989283, 2023).
Obesity (37 papers, 2008 to 2025). Accumulation of substantial excess body fat. "Recent studies have identified that lung tissue expresses higher expression levels of Csf2 under conditions of obesity, potentially through elevated recruitment of immune cell populations that also express Csf2." (PMID 33670906, 2021). "Obesity-activated lung stromal cells also enhanced recruitment of myeloid-lineage cells through elevated expression of CSF2." (PMID 33670906, 2021). "Together, these results suggest that circulating factors induced by obesity can promote Csf2 expression in lung stromal cells." (PMID 33670906, 2021). "Our results indicated that these bone marrow-derived cells may be recruited from the circulation into lung tissue by lung stromal cells in obesity through locally elevated CSF2 as well as S100A8, which has been shown to promote accumulation of myeloid lineage cells at metastatic sites in vivo." (PMID 33670906, 2021).
lung disease (34 papers, 2011 to 2026). "Importantly, the ratio of cholesterol to total phospholipids in surfactant was already elevated 3-fold in Csf2−/− mice at 6 weeks compared to WT, and remained elevated but did not increase further at 12, 24, and 36 weeks, whereas PAP lung disease severity increased steadily." (PMID 28860566, 2017).
psoriasis (34 papers, 2010 to 2025). An autoimmune condition characterized by red, well-delineated plaques with silvery scales that are usually on the extensor surfaces and scalp. "Mechanistically, this psoriasis protection was mediated by IκBζ deficiency in keratinocytes abrogating the induction of specific proinflammatory target genes, including Cxcl5, Cxcl2, Csf2, and Csf3, in response to IL-17A or IL-36." (PMID 31622280, 2019).
Crohn disease (33 papers, 2013 to 2026). A gastrointestinal disorder characterized by chronic inflammation involving all layers of the intestinal wall, noncaseating granulomas affecting the intestinal wall and regional lymph nodes, and transmural fibrosis. "Analysis of a publically available dataset of colon tissue from healthy controls and IBD patients showed a significant increase in CSF2 gene expression in the colons of patients with either Crohn’s disease or ulcerative colitis compared with controls." (PMID 26780670, 2016).
eosinophilia (33 papers, 2006 to 2025). "CRSwNP-dominant regulators are engaged in T2 inflammation or eosinophilia, such as ERBB, TNF pathway, inflammatory and host defense, cytokine regulators and their cytokines, such as CSF2 or IL4, and angiogenetic factors." (PMID 36982612, 2023).
Allergy (32 papers, 2005 to 2025). An allergy is an immune response or reaction to substances that are usually not harmful. "Curcumin was reported to repress CSF2 in a concentration-dependent manner in allergic diseases." (PMID 35405942, 2022). "The analysis implicated a number of genes with roles in allergy and inflammation, including pro-inflammatory cytokines (IL1A, IL1B, IL6, IL8 and TNF) and factors involved in immune cell activation and recruitment (SELE, SELL, SELP, ICAM1, CSF2, CSF3, CCL2 and CXCL2)." (PMID 21067579, 2010).
fungal infection (31 papers, 2013 to 2025). "Similarly, mice lacking GM-CSF (Csf2−/−) or the receptor β chain (Csf2rb−/−) develop PAP and display increased susceptibility to a range of bacterial and fungal infections, which is associated with impaired innate functions of AM." (PMID 24699679, 2014).
gastric cancer (31 papers, 1998 to 2025). A primary or metastatic malignant neoplasm involving the stomach. "In summary, these findings indicate that the m6A modification and gene expression of CSF2 increase in tumor-conditioned MSCs and a high level of CSF2 in gastric cancer tissues is linked to poor prognosis." (PMID 37865637, 2023). "Previous studies have found that CSF2 facilitates tumor progression in malignancies such as bladder, prostate, and gastric cancers by promoting neovascularization within the tumor microenvironment." (PMID 41216204, 2025). "Immunofluorescence results showed that MSC marker α-SMA was also predominantly localized at the base of gastric glands and co-localized with CSF2 in gastric cancer tissues." (PMID 37865637, 2023). "Collectively, these findings indicate that IGF2BP2/CSF2/Notch1 axis reprograms MSCs to promote gastric cancer progression." (PMID 37865637, 2023). "We found a significant increase in the expression and N6-methyladenosine (m6A) modification levels of colony-stimulating factor 2 (CSF2) in gastric cancer MSCs." (PMID 37865637, 2023). "TCGA database analysis also revealed a higher level of CSF2 in gastric cancer specimens than normal gastric tissues." (PMID 37865637, 2023). "We next aimed to elucidate the involvement of IGF2BP2/CSF2/Notch1 axis in regulating the phenotype and function of MSCs in gastric cancer." (PMID 37865637, 2023). "Collectively, these results suggest an important role of IGF2BP2/CSF2/Notch1 axis in regulating MSCs reprogramming in gastric cancer." (PMID 37865637, 2023). "Immunohistochemical analysis of pathological sections from gastric cancer patients who underwent surgical treatment demonstrated predominant CSF2 expression at the base of gastric glands in mucosal tissues." (PMID 37865637, 2023). "Conversely, CSF2 knockdown suppressed the tropism of P-MSCs towards gastric cancer cells (53.83 ± 2.06 in CSF2 knockdown group and 97.17 ± 2.91 in control group)." (PMID 37865637, 2023). "The inhibition of gastric cancer cell proliferation, migration, and drug resistance by the supernatant from P-MSCs with CSF2 knockdown was also enhanced by Notch1 co-inhibition." (PMID 37865637, 2023). "Collectively, these findings indicate that CSF2 plays a critical role in regulating the pro-tumor phenotype and function of MSCs in gastric cancer." (PMID 37865637, 2023). "To further investigate the role of CSF2-mediated reprogramming of MSCs in promoting gastric cancer progression in vivo, we conducted subcutaneous xenograft mouse tumor models with HGC-27 cells together with MSCs from different sources (1:1 ratio)." (PMID 37865637, 2023). "The supernatants from MSCs with CSF2 overexpression and P-MSCs with CSF2 knockdown were collected and used to treat human gastric cancer cells." (PMID 37865637, 2023). "Compared to that from control MSCs, the supernatant from MSCs with CSF2 overexpression promoted gastric cancer cell viability, cell colony formation and migration." (PMID 37865637, 2023). "CSF2 upregulation induced the transition of MSCs towards a cancer-promoting phenotype, thereby facilitating the proliferation, migration, and invasion of gastric cancer cells." (PMID 37865637, 2023). "In MSCs with CSF2 overexpression, a notable enhancement in tropism towards gastric cancer cells (57.33 ± 1.96) was observed, compared to control group (38.67 ± 1.86)." (PMID 37865637, 2023). "In this study, we identified an elevation of colony stimulating factor 2 (CSF2) in gastric cancer tissue-derived mesenchymal stem cells (GC-MSCs) through m6A-dependent mechanism." (PMID 37865637, 2023). "Our study highlights a critical role of IGF2BP2-mediated m6A modification of CSF2 in reprogramming MSCs, which presents a promising therapeutic target for gastric cancer." (PMID 37865637, 2023). "In patients who experienced relapse within 1 year after surgery, the positive rate of CSF2 in gastric cancer tissues was approximately 46%." (PMID 37865637, 2023).
gastric cancer (continued). "In patients who did not experience relapse within 3 years after surgical treatment, the positive rate of CSF2 in gastric cancer tissues was approximately 9%." (PMID 37865637, 2023). "In gastric cancer, CSF2 mediates chemotherapy responses and leads to tumor progression." (PMID 41154660, 2025). "Furthermore, the co-transfection of Notch1 inhibited the stimulatory effects of the supernatant from CSF2 overexpression MSCs on gastric cancer cell proliferation, migration and drug resistance." (PMID 37865637, 2023). "The identified IGF2BP2/CSF2/Notch1 axis provides additional evidence for the epigenetic regulation of MSCs within the tumor microenvironment and offers a new therapeutic strategy for gastric cancer." (PMID 37865637, 2023). "CSF2 gene overexpression induced the reprogramming of normal MSCs into cancer-promoting MSCs, thereby enhancing the proliferation, migration, and drug resistance of gastric cancer cells through the secretion of various pro-inflammatory factors." (PMID 37865637, 2023). "Additionally, we demonstrated that the m6A reader IGF2BP2 bound to and stabilized CSF2 mRNA in gastric cancer MSCs." (PMID 37865637, 2023). "Notably, overexpression of IGF2BP2 mimicked the effect of CSF2 on MSCs, promoting gastric cancer progression." (PMID 37865637, 2023). "Hence, these findings indicate that CSF2 acts as a downstream target of IGF2BP2 to promote the reprogramming of MSCs in gastric cancer." (PMID 37865637, 2023). "Furthermore, the expression of IGF2BP2 positively correlated with that of CSF2 in gastric cancer tissues with a correlation coefficient of 0.54." (PMID 37865637, 2023). "In this study, we provided evidence showing that MSCs can be reprogrammed towards a pro-tumor phenotype by gastric cancer cells through an epigenetic mechanism, which involves increased IGF2BP2-mediated m6A modification and stability of CSF2 mRNA." (PMID 37865637, 2023). "Notch1 co-transfection partially reversed the effects of CSF2 on MSC phenotype and function, including the tropism towards gastric cancer cells, the enhanced FAP and α-SMA expression, and the secretion of GM-CSF, FGF, and PDGF-BB." (PMID 37865637, 2023). "Conversely, co-transfection of Notch1 inhibitors in P-MSCs with CSF2 knockdown showed rescued the inhibitory effect of CSF inhibitors, including augmented tropism towards gastric cancer cells, enhanced expression of FAP and α-SMA, elevated expression of inflammatory factors GM-CSF, FGF, and PDGF-BB." (PMID 37865637, 2023).
inflammatory bowel disease (31 papers, 2015 to 2025). A spectrum of small and large bowel inflammatory diseases of unknown etiology. "CSF2 encodes a cytokine that controls the production, differentiation, and function of granulocytes and macrophages and is associated with eosinophil count and inflammatory bowel disease." (PMID 33456716, 2020).
Stroke (30 papers, 2007 to 2025). Sudden impairment of blood flow to a part of the brain due to occlusion or rupture of an artery to the brain. "This conjecture is further supported by the association of stroke with colony stimulating factor 2 (CSF2), a protein necessary for the survival, proliferation and differentiation of leukocyte progenitors." (PMID 20401335, 2009).
myeloma (28 papers, 2008 to 2024). "In addition, IL-3 and IL-5 share a common signal transduction chain, KH97, with CSF2, which can increase the sensitivity of myeloma cells to these cytokines." (PMID 37250588, 2023). "Interestingly, CSF2 does not directly act as a growth factor in myeloma, but instead sensitizes cells to IL-6." (PMID 37250588, 2023).
pulmonary fibrosis (28 papers, 2005 to 2025). Chronic progressive interstitial lung disorder characterized by the replacement of the lung tissue by connective tissue, leading to progressive dyspnea, respiratory failure, or right heart failure. "When CSF2 is overexpressed in the body, activated monocytes induce T cell death, resulting in lymphopenia, pathological hyperinflammatory immune response, pulmonary fibrosis and severe immune cell infiltration." (PMID 36034710, 2022). "For example, lung fibrosis-associated genes (CSF3, IL8, CSF2, IL6, TNF, MMP9, IL1B and PDGFB) were significantly upregulated in SARS-CoV-2-infected NHBE cells." (PMID 32698440, 2020). "Our analysis showed that eight genes (CSF2, CSF3, CXCL2, CXCL8, IL1B, IL6, MMP9, and TNF) are significantly overlapping with the lung fibrosis pathway with p-value 9.35e-11." (PMID 33362771, 2020).
Alzheimer disease (27 papers, 2012 to 2025). A progressive, neurodegenerative disease characterized by loss of function and death of nerve cells in several areas of the brain leading to loss of cognitive function such as memory and language. "Our data underscore a protective relationship between CSF2 and Alzheimer’s disease related outcomes, and further suggest that CSF2 may also have relevance in FTD spectrum disorders." (PMID 39816189, 2025).
acute myeloid leukemia (26 papers, 2002 to 2025). Acute myeloid leukemia (AML) is a group of neoplasms arising from precursor cells committed to the myeloid cell-line differentiation. "GM-CSF (CSF-2) is a clinically available recombinant cytokine used to promote myeloid reconstitution after bone marrow transplantation or following induction chemotherapy in patients with acute myelogenous leukaemia." (PMID 30413827, 2019).
bladder cancer (26 papers, 1997 to 2025). "Additionally, it has been shown that adverse clinical outcomes are caused by CSF2 overexpression in bladder cancer." (PMID 37213667, 2023). "Buytaert and colleagues recently investigated the transcriptional changes in bladder cancer cells upon hypericin-mediated low-dose PDT and observed upregulation of the granulocyte-macrophage colony-stimulating factor (CSF2) and TLR2 genes besides IL8." (PMID 21738796, 2011).
breast tumor (26 papers, 2008 to 2025). "Moreover, VEGF-R1-expressing MAMs produced GM-CSF/CSF2 to promote metastatic growth of breast tumors in vivo." (PMID 30597969, 2018). "We saw a significant increase in Csf2 expression in PyMT/p11-KO tumors but Csf2 has not been shown to correlate with macrophage infiltration in breast tumors." (PMID 33297495, 2020).
periodontitis (25 papers, 2006 to 2025). An acute or chronic inflammatory process that affects the tissues that surround and support the teeth. "Elevated levels of both IFN‐γ and CSF2 have been observed in the GCF of patients with periodontitis relative to a control group." (PMID 40344491, 2025). "Further, systemic SIM treatment for 4 weeks decreased RANKL and colony stimulating factor 2 expressions in periodontal tissues of obese rats with LPS-induced periodontitis, suggesting an inhibitory effect of SIM on expression of osteoclastogenesis factors in rats with metabolic syndrome." (PMID 30413166, 2018).
tuberculosis (25 papers, 2012 to 2025). A chronic, recurrent infection caused by the bacterium Mycobacterium tuberculosis. "However, IL-10 may be involved in the mutual regulation of the levels of CSF-2 and CSF-3 to balance the levels of these three cytokines, which is associated with the risk of tuberculosis." (PMID 37818041, 2023). "Therefore, we predicted central DEGs in the PPI network and noted strong interactions between TNF, IL-6, IL-10, IL-1β, CSF-2, IL-4, CXCL8, IFN-γ, IL-1α, and CXCL1, all of which are strongly associated with tuberculosis." (PMID 37818041, 2023). "HIV-tuberculosis patients had higher supernatant concentrations of CSF-3, IFN-ɣ, and IL-1-receptor-antagonist (IL-1RA) and lower concentrations of CSF-2, IL-12p40, IL-1β, IL-6, and TNF-α." (PMID 28369200, 2017).